IL1R1 (interleukin 1 receptor type 1)
Description:
Receptor for IL1A, IL1B and IL1RN. After binding to interleukin-1 associates with the coreceptor IL1RAP to form the high affinity interleukin-1 receptor complex which mediates interleukin-1-dependent activation of NF-kappa-B, MAPK and other pathways. Signaling involves the recruitment of adapter molecules such as TOLLIP, MYD88, and IRAK1 or IRAK2 via the respective TIR domains of the receptor/coreceptor subunits. Binds ligands with comparable affinity and binding of antagonist IL1RN prevents association with IL1RAP to form a signaling complex. Involved in IL1B-mediated costimulation of IFNG production from T-helper 1 (Th1) cells.
Synonyms: IL-1RT1; IL-1R-alpha; CD121a; IL1R; IL1RA; D2S1473; CRMO3; P80
Tractability: Small molecule: a high-quality ligand is known. Antibody: a drug acting on it is in phase 2 or 3 trials; UniProt places it where antibodies can reach, with high confidence; its Gene Ontology location is reachable by antibodies, with high confidence; UniProt predicts a signal peptide or a membrane-spanning region; the Human Protein Atlas places it where antibodies can reach. PROTAC: ubiquitination databases record sites on it; a small molecule that binds it is known. Other modalities: an approved drug acts on it.
Target class: Membrane receptor
Gene: Protein-coding gene on chromosome 2 (102,063,933 to 102,179,874, forward strand). Ensembl gene ENSG00000115594.
Subcellular location: Membrane; Cell membrane; Secreted
Subcellular location (Human Protein Atlas): Nucleoplasm; Vesicles; Cytosol; Plasma membrane; Predicted to be secreted
Pathways (Reactome):
Immune System: Interleukin-1 signaling; Interleukin-10 signaling
Disease: Potential therapeutics for SARS
Gene Ontology:
Molecular function: interleukin-1 receptor activity; platelet-derived growth factor receptor binding; protein binding; interleukin-1, type I, activating receptor activity; transmembrane signaling receptor activity; cytokine receptor activity; NAD+ nucleosidase activity, cyclic ADP-ribose generating
Biological process: interleukin-1-mediated signaling pathway; positive regulation of canonical NF-kappaB signal transduction; positive regulation of phosphatidylinositol 3-kinase/protein kinase B signal transduction; positive regulation of platelet-derived growth factor receptor signaling pathway; positive regulation of T-helper 1 cell cytokine production; positive regulation of type II interferon production; response to interleukin-1; cell surface receptor signaling pathway; immune response; negative regulation of inflammatory response; negative regulation of interleukin-1-mediated signaling pathway; regulation of inflammatory response; smooth muscle adaptation; signal transduction
Cellular component: membrane; cell surface; plasma membrane; extracellular region
Genetic constraint (gnomAD): Loss-of-function variants: 8 observed, 22.94 expected, observed/expected ratio (o/e) 0.35, 90% interval 0.2 to 0.63. The upper end of that interval is the gene's LOEUF score, 0.63, which puts it in group 2 of 6, group 1 being the genes least tolerant of losing a copy. Missense variants: 352 observed, 487.91 expected, observed/expected ratio (o/e) 0.72, 90% interval 0.66 to 0.79. Synonymous variants: 174 observed, 171.82 expected, observed/expected ratio (o/e) 1.01, 90% interval 0.89 to 1.15.
Homologues: Orthologues: chimpanzee IL1R1 (99% identical), macaque IL1R1 (95% identical), dog IL1R1 (78% identical), rabbit IL1R1 (74% identical), pig IL1R1 (73% identical), mouse Il1r1 (69% identical), rat Il1r1 (67% identical), guinea pig IL1R1 (64% identical), tropical clawed frog il1r1 (35% identical). Paralogues in human: IL1RL2 (40% identical), IL1RL1 (27% identical), IL1RAPL2 (26% identical), IL1RAPL1 (26% identical), IL18R1 (24% identical), IL18RAP (22% identical), IL1RAP (21% identical), IL1R2 (16% identical), SIGIRR (13% identical), LAG3 (12% identical).
Diseases named in the same sentence as IL1R1 in open-access papers:
IL1R1 is named in the same sentence as 416 diseases in open-access papers, as found by Europe PMC text mining. Sharing a sentence is not in itself a finding about the gene and the disease. The quoted sentences say what the papers report.
breast cancer (56 papers, 2008 to 2024). A primary or metastatic malignant neoplasm involving the breast. "Signaling through GPER-1 has been shown to trigger the expression of IL-1β and IL-1R1 in cancer-associated fibroblasts and breast cancer cells, respectively." (PMID 33117280, 2020). "The results of the association between IL-1B, IL1R1 polymorphisms and breast cancer risk have significant." (PMID 29719585, 2018). "Three single nucleotide polymorphisms (SNPs) identified in IL1B, IL1R1 gene are thought to influence breast cancer risk." (PMID 29719585, 2018). "The expression level of the genes analyzed in this study may have a predictive value for breast cancer overall survival since it indicated that IL1R1 and ILRAP gene expression presented an increased risk in breast invasive carcinoma-LumA and -LumB patients." (PMID 39201290, 2024). "As a well-characterized proinflammatory cytokine, IL-1β is associated with more aggressive phenotype and higher tumor grade in breast cancer, and genetic variations of IL-1β and IL-1R1 may predict breast cancer risk and prognosis." (PMID 29670904, 2018). "Taken together with our finding that IL1B, IL1R1 gene three SNP are also associated with the risk for the disease, we suggest that inflammation via innate and adaptive immunity contributes to multifactorial hereditary predisposition to pathogenesis of the breast cancer." (PMID 29719585, 2018). "Early in tumorigenesis, IL-1R1 signaling suppresses mammary tumor cell proliferation and inhibits breast cancer outgrowth and pulmonary metastasis." (PMID 39190284, 2024). "We also checked the frequency of occurrence of various breast cancer sub-types in IL1R1 high and low samples." (PMID 39728924, 2024). "Despite this, the importance of the expression of these genes in breast cancer is such that high IL1R1 or IL1RAP is strongly related to patient survival." (PMID 39201290, 2024). "For example, it was demonstrated that IL1R1 protein induces CTC proliferation in breast cancer (BRCA), and high IL1R gene expression corresponds to inferior prognosis in the TCGA-BRCA cohort as well as in many other cancers." (PMID 37006265, 2023). "A similar function for IL-1A and IL-1B has also been reported: IL-1A and IL-1B produced by breast cancer cells can display the same function by equally activating IL1R1 in lung fibroblasts, which support metastatic colonisation." (PMID 34290237, 2021). "We recently identified the pro-inflammatory cytokine Interleukin-1B (IL-1B) as a marker of breast cancer bone metastasis and showed that pharmacological targeting of IL-1B or its receptor (IL1R1) impairs bone metastasis." (PMID 34290237, 2021). "In order to address the role of tumour-derived IL-1B signalling in an immune-competent syngeneic model, we orthotopically injected IL1R1-overexpressing E0771 mouse mammary tumour cells in IL1R1fl/fl and IL1R1−/− mice." (PMID 34290237, 2021). "Intriguingly, GPER was also shown to trigger the activation of the IL-1β/IL1R1 transduction signaling, which in turn promoted inflammatory responses and aggressive features of breast cancer cells." (PMID 32778144, 2020). "In line with this, when E0771 mouse mammary tumor cells were injected into syngeneic Il1r1−/− mice, metastatic colonization of the lungs was also significantly reduced." (PMID 32198421, 2020). "The pro-inflammatory cytokine interleukin-1β (IL-β) and its cognate receptor IL1R1 contribute to the initiation and progression of breast cancer determining pro-tumorigenic inflammatory responses." (PMID 32778144, 2020). "In this study, Simões, Clarke and colleagues show that anti-estrogen treatments select for ALDH+ breast cancer stem cells expressing IL1R1, which can be targeted by a specific inhibitor." (PMID 32707076, 2020). "In this regard, our and other previous studies have demonstrated that an estrogen-induced feedforward loop couples the IL-1β induction in CAFs to the IL1R1-stimulatory action elicited in breast cancer cells." (PMID 32778144, 2020).
breast cancer (continued). "In PyMT/ Il1a-/- and PyMT/Il1r1-/- mice, IL-1R1 signaling suppresses mammary tumor cell proliferation early in tumorigenesis and facilitates breast cancer outgrowth with pulmonary metastasis." (PMID 33031059, 2020). "Immunohistochemistry for S100A4, Fibronectin, RAS, IL-1B, IL-1R1 and γ Catenin was performed on mammary tumours and metastases in human bone implants." (PMID 31783893, 2019). "GPER activation upregulates interleukin-1 receptor-1 (IL1R1) expression on breast cancer cells and interleukin (IL)-1β expression on cancer associated fibroblasts in a signalling loop to encourage invasive features of breast cancer." (PMID 29899833, 2018). "Here, we demonstrate that signalling mediated by the G protein estrogen receptor (GPER) triggers IL1β and IL1R1 expression in CAFs and breast cancer cells, respectively." (PMID 27072893, 2016). "Altogether, these results suggest that E2 and G-1 trigger the up-regulation of IL1R1 in breast cancer cells through GPER-mediated signalling." (PMID 27072893, 2016). "Considering that E2 and G-1 trigger the expression of IL1β in CAFs and IL1R1 in breast cancer cells, we then assessed that conditioned medium from CAFs exposed to E2 and G-1 does induce PTGES protein expression in SkBr3 and MCF-7 cells exposed to E2 or G-1." (PMID 27072893, 2016). "In mouse models, IL-1B and its receptor (IL-1R1) are upregulated in breast cancer cells that metastasise to bone compared with cells that do not." (PMID 27765923, 2016). "In breast cancer, HIF-1α and the G protein-coupled estrogen receptor (GPER) signaling pathway stimulate the expression of VEGF in CAFs, while GPER in breast cancer CAFs induces interleukin-1β (IL-1β) to express interleukin-1 receptor 1 (IL1R1) in breast cancer cells." (PMID 39192979, 2024). "(A) Key Immune marker expression (TAM markers, TAM related chemokines, T cell markers), TERT and TERC were plotted for fold change of transcript level expression (IL1R1 high / IL1R1 low) and adjusted p-values in breast cancer (BRCA) samples categorized as IL1R1 high or low from TCGA." (PMID 39728924, 2024). "Finally, the importance of the expression of these genes in breast cancer is such that high IL1R1 or IL1RAP is strongly related to patient survival." (PMID 39201290, 2024). "In breast cancer, IL-1-mediated IL-1R1 signaling is tumor-suppressive." (PMID 39190284, 2024). "When breast cancer transcriptomic data from TCGA was segregated into high and low IL1R1 groups." (PMID 39728924, 2024). "Gene expression associated with ER status in breast cancer patients was analyzed and results indicated that IL1R1 and IL1RN gene expression levels were non-significant among patients, whereas those with high IL6ST expression levels had a positive ER status." (PMID 39201290, 2024). "Interestingly, ALDH and IL‐1 receptor (IL1R1) double‐positive CSCs are enriched following antiestrogen therapy and held responsible for the treatment failure in breast cancer patients, which can be attenuated with IL1R1 antagonists such as anakinra." (PMID 36694633, 2023). "Likewise, incubation of MCF-7 with 2 and 5 μM linoelaidic acid increased the expression levels of interleukin 1 receptor type 1(IL-1r1) by 1.38 and 2.28-fold compared with control breast cancer cells." (PMID 37644076, 2023). "Additionally, E2 and G-1 induced IL-1β expression in CAFs, while in MCF-7 and SKBR3 breast cancer cell lines they promoted IL1R1 expression, stimulating migration and invasion of breast cancer cells." (PMID 32973677, 2020). "The inhibition of IL-1R1 and reduced bone metastasis in our mouse model shows the role of this signalling axis in breast cancer metastasis to bone, but further studies are needed to elucidate whether IL-1B and/or IL-1A are primarily involved in this process." (PMID 29760166, 2018).
breast cancer (continued). "In particular, using a spontaneous murine mammary tumour model (MMTV-PyMT), Dagenais and colleagues have shown that IL-1R1 signalling suppresses mammary tumour cell proliferation early in tumourigenesis and reduces breast cancer outgrowth and metastasis in the lungs." (PMID 29760166, 2018). "Collectively, these findings suggest that estrogenic GPER signalling generates a feedforward loop that couples IL1β induction in CAFs to IL1R1 expression by cancer cells, hence contributing to the functional cross-talk between the tumor microenvironment and breast cancer cells." (PMID 27072893, 2016). "On the basis of these results, it could be assumed that estrogenic GPER signalling couples the expression of both IL1β in CAFs and IL1R1 in breast cancer cells, thus generating a feedforward IL1beta/IL1R1 response." (PMID 27072893, 2016). "Indeed, IL-1β is considered as a master cytokine in the progression of breast cancer as its production has been found correlated with advanced diseases, whereas the IL1R1 inhibition by the antagonist anakinra was shown to prevent the growth of breast cancer and the bone metastasis in mouse models." (PMID 32778144, 2020). "Finally, our results suggest that patients diagnosed with malignant ER+ breast cancer may benefit from combination therapy consisting of IL1R1 and PDGFRβ blockers to enhance the effectiveness of endocrine therapies such as Tam." (PMID 31419632, 2019). "We, next, used publicly available TCGA gene expression data of breast cancer samples (BRCA) to assess the effect of IL1R1 expression on cancer prognosis." (PMID 39728924, 2024). "We further performed ChIP-qPCR spanning +200 to –1000 bp of the IL1R1 TSS to confirm promoter TRF2 binding across multiple cell lines- HT1080 fibrosarcoma, MDAMB231 breast cancer, HEK293T immortalised kidney and MRC5 fibroblast cells." (PMID 39728924, 2024). "Dendritic cell infiltration showed a positive correlation with IL1R1, ILRN, and ILRAP gene expression in breast cancer Basal and Luminal A patients." (PMID 39201290, 2024). "On the other hand, the macrophage infiltration showed a positive correlation with IL1R1, IL1RAP, and IL6ST gene expression in all subtypes of patients with breast cancer." (PMID 39201290, 2024). "Neutrophil infiltration had a direct relationship with the expression of IL1R1, IL1RN, IL1RAP, IL6ST, CXCL3, CXCL5, and CXCL6 in most of the subtypes of the breast cancer patients analyzed." (PMID 39201290, 2024). "The function of IL-1 signalling on viability and migration and invasion of breast cancer cells was assessed, in vitro, upon IL1B or IL1R1 overexpressing or treatment with anti-IL-1 signalling." (PMID 36230739, 2022). "In summary, the analysis of breast cancer overall survival indicated that a high level of IL1R1 expression in LumA patients presented no survival after 150 months." (PMID 39201290, 2024). "To note, the protein–protein interaction network of PIK3R1, IL1R1, MMP11, GOLM1, and VAV3 altogether connected by EGFR merits further work to understand the mechanism and develop an ideal treatment strategy for invasive small tumor-size breast cancers." (PMID 39190284, 2024). "The relationship between ESR1 gene expression with IL1R1 or IL1RN genes has not been described for breast cancer." (PMID 39201290, 2024). "In contrast, the IL-1β/IL-1R1/β-catenin signaling pathway that regulates c-MYC, cyclin D1 (CCDN1), SNAIL1, and matrix metallopeptidases (MMP) 2 expression promotes proliferation, migration, and invasion in breast cancer." (PMID 32397236, 2020). "For instance, IL1β/IL1R1 system has been shown to up-regulate PTGES, which is a key enzyme involved in the production of COX2 and prostaglandin E2 that promote the motility of breast cancer cells." (PMID 27072893, 2016).
breast cancer (continued). "We found that IL1R1 (Il1r1 interleukin 1 receptor, type I), BCAR3 (breast cancer anti-estrogen resistance 3), KCNH2 (potassium channel, voltage gated related subfamily H, member 2), PIR (pirin), and ZDHHC23 (zinc finger, DHHC-type containing 23) were differentially expressed." (PMID 27536776, 2016). "In addition, IL1R1 has been found to be upregulated in ALDH+ cells and plays a crucial role in driving cancer stem cell (CSC) activity, which can lead to resistance to adjuvant endocrine therapies, including tamoxifen and fulvestrant, in breast cancer and promote bone metastasis." (PMID 37207166, 2023). "Similarly, we expanded the breast cancer input layer with the hyaluronan-mediated motility receptor (HMMR) connected to FN1; the TGFBR connected to SNAI1 and SNAI2; the interLeukin 1 receptor type I (IL1R1) and the thyroid hormone receptor beta (THRB) connected to TRAF1 and MYC, respectively." (PMID 28775339, 2017).
rheumatoid arthritis (42 papers, 2009 to 2025). A chronic, systemic autoimmune disorder characterized by inflammation in the synovial membranes and articular surfaces. "In particular, up-regulation of IL-1R1 via its agonistic ligands consisting of IL-1β and IL-1α is implicated in a variety of human diseases, such as rheumatoid arthritis, psoriasis, type I diabetes, amyotrophic lateral sclerosis, and dry-eye disease." (PMID 35523814, 2022). "However, persistent activation of the IL-1/IL-1R1 complex is intimately linked with the pathogenesis of a plethora of disease states, such as rheumatoid arthritis, type 2 diabetes, autoinflammatory diseases, cancer and neuroinflammation-associated neurodegenerative diseases." (PMID 35269739, 2022). "For example, anakinra is an FDA-approved recombinant IL-1R1 antagonist used to treat rheumatoid arthritis, neonatal onset multisystem inflammatory disease, and deficiency of interleukin-1 antagonist." (PMID 41390483, 2025). "Recombinant IL-1Ra (generic anakinra) is fully active in blocking the IL-1 receptor 1 (IL-1R1), and thus the activities of IL-1α and IL-1β, and is approved for the treatment of rheumatoid arthritis and several other diseases." (PMID 35448559, 2022). "MEDI8968, a fully human immunoglobulin G2 monoclonal antibody that binds selectively to IL-1R1 to inhibit its activation by IL-1α and IL-1β, has been investigated in subjects with rheumatoid arthritis and osteoarthritis." (PMID 28793896, 2017). "It has been shown that inhibiting IL-1β/IL-1R1 axis by anakinra, a recombinant IL-1R1 antagonist approved to treat rheumatoid arthritis, is sufficient to reverse DN pathology in mouse model." (PMID 27706238, 2016). "Anakinra is designed to treat rheumatoid arthritis by competitively binding to IL-1R1 thereby inhibiting the action of elevated levels of the pro-inflammatory cytokine IL-1." (PMID 23516507, 2013). "Furthermore, the development of anti-IL-1R1 monoclonal antibodies for rheumatoid arthritis, Still’s disease, and osteoarthritis underscores the potential for targeting this pathway in IBD." (PMID 39595128, 2024). "Both IL-1α and IL-1β bind to the IL-1 type 1 receptor (IL-1R1), inducing a wide range of secondary inflammatory mediators and playing critical roles in regulating immune and inflammatory processes, such as rheumatoid arthritis (RA) and systemic lupus erythematosus." (PMID 40371323, 2025). "Besides, in the rheumatoid arthritis, the AUC values for CEBPA, CEACAM1, BTG3, and IL1R1 were 0.609, 0.730, 0.686, and 0.608, respectively and diagnostic model achieved a high AUC of 0.844 on this cohort." (PMID 39113685, 2024). "An earlier study revealed that in the context of type 1 inflammation, OSM enhances the expression of OSMR and IL-1R1 in synovial fibroblasts, thereby amplifying the pathological effects of both OSM and IL-1 in rheumatoid arthritis (RA)." (PMID 38137445, 2023).